CD244 (CD244 molecule)
Diseases named in the same sentence as CD244 in open-access papers (continued):
Sharing a sentence is not in itself a finding about the gene and the disease.
myeloma (7 papers, 2015 to 2025). "CD244 has been shown to be overexpressed in the exhausted T cells in chronic infections, such as in hepatitis B, as well as in some malignancies, including multiple myeloma and AML." (PMID 37634081, 2023). "Elotuzumab, indicated in combination with lenalidomide and dexamethasone for the treatment of patients with multiple myeloma who have received one to three prior therapies, and ALDESLEUKIN, an antineoplastic agent, have also been identified as drugs targeting CD244." (PMID 39092217, 2024).
acute myeloid leukemia (6 papers, 2017 to 2025). Acute myeloid leukemia (AML) is a group of neoplasms arising from precursor cells committed to the myeloid cell-line differentiation. "In particular, a study reported that CD244 was downregulated in the NK cells of patients with acute myeloid leukemia (AML), and that NK cell activity positively correlated with progression-free survival of these patients." (PMID 33841431, 2021). "In addition, the simultaneous increase of TOX, along with CD244, PD-1, and Tim-3, in T cells was found to correlate with T cell exhaustion in acute myeloid leukemia." (PMID 39758401, 2025). "We discovered that CD244 expression in AML (acute myeloid leukemia) was not only significantly negatively associated with differentiation and hypoxia but was also positively associated with EMT (epithelial-mesenchymal transition)." (PMID 38633624, 2024). "The increase in the proportion of CD244+PD-1+ T cells was found in acute myeloid leukemia and non-Hodgkin’s lymphoma significantly, that may be related to the occurrence and development of tumor." (PMID 38035110, 2023).
autoimmune disease (6 papers, 2012 to 2025). A disorder resulting from loss of function or tissue destruction of an organ or multiple organs, arising from humoral or cellular immune responses of the individual to their own tissue constituents. "In the context of autoimmune diseases, CD244/CD48 co-stimulatory signals are primarily involved in regulating immune cell functions and influencing episodes of autoimmune disease." (PMID 38980684, 2025). "Our findings provide new insights into the potential involvement of CD244 in regulating the balance between immunosuppressive monocytes and pro-inflammatory macrophages in the context of both autoimmune diseases and cancers." (PMID 38424542, 2024). "In-depth studies reported that CD244 functions in many immune-related diseases, such as autoimmune diseases, infectious diseases, and cancers, and its action is essential for the onset and progression of these diseases." (PMID 33841431, 2021). "Based on our study, we hypothesize that CD244 might restrain monocyte differentiation in autoimmune diseases, thereby curtailing disease progression." (PMID 38424542, 2024). "Co-signaling molecules, such as CD244/CD48, affect the onset of autoimmune diseases by regulating various functions of immune cells and by maintaining or altering the balance of immune responses." (PMID 33841431, 2021). "RRA discovery study suggested that CD160 was the most significant gene aberrantly expressed in autoimmune diseases (Adjusted P = 5.9E-12), followed by CD58 (Adjusted P = 5.7E-06) and CD244 (Adjusted P = 9.5E-05)." (PMID 30842773, 2019). "CD244 (SLAM 4; signaling lymphocytic activating molecule 4) binds to the ligand CD48 on cells nearby and conveys stimulatory or inhibitory signals to immune response cells, contributing to the emergence and advancement of autoimmune disorders." (PMID 38474367, 2024). "Findings from the RRA discovery study suggested that CD160 was the most significant gene aberrantly expressed in autoimmune diseases (Adjusted P = 5.9E-12), followed by CD58 (Adjusted P = 5.7E-06), CD244 (Adjusted P = 9.5E-05), LGALS9 (Adjusted P = 0.001) and CD27 (Adjusted P = 0.005)." (PMID 30842773, 2019).
breast carcinoma (5 papers, 2013 to 2024). "In a large analysis of immune checkpoint genes in breast cancer, SLAMF4/CD244 expression in tumors was found to be lower than that in healthy breast tissue." (PMID 38476238, 2024). "CD244 mRNA levels have been found to be downregulated in breast cancer tissue." (PMID 36945037, 2023).
chronic hepatitis C (5 papers, 2011 to 2019). "CD244 is upregulated in chronic hepatitis C (CHC) patients and the increased expression of CD244 is positively associated with the level of PD-1 expression." (PMID 28703774, 2017). "In patients with acute and chronic hepatitis C, CD244/2B4 is found to be present on virus-specific CD8+ T cells and is a marker for CD8+ T cell dysfunction." (PMID 23638187, 2013).
glioblastoma (5 papers, 2022 to 2024). The most malignant astrocytic tumor (WHO grade IV). "In a study investigating immune system-related plasma proteins in glioblastoma, researchers found that high CD244 levels were associated with long progression-free survival, which seems contradictory to our results." (PMID 35936722, 2022). "In addition, CD244 expression in GBM (glioblastoma) was significantly and negatively associated with invasion, and CD244 expression in UM (uveal melanoma) was significantly negatively associated with DNA repair." (PMID 38633624, 2024). "There, genes with a higher expression in glioblastoma compared to astrocytoma were VEGFA, 4EBP1, CCL2, PLAU (uPA), CXCL8 (IL8), CXCL10 (IP10), CASP8, HGF, LIF, CD40, CDCp1, TNFRSF11B (OPG), CD274 (PD-L1), IL6, CXCL1, CCL20 (MIP3α), CCL8 (MCP2), CD244, MMP1, TNFRSF9, CXCL6, MMP10, FGF5)." (PMID 35301393, 2022). "In contrast, other tumors such as PCPG, LIHC, KIRP, glioblastoma multiforme (GBM), COAD, BLCA, SARC, prostate adenocarcinoma (PRAD), BRCA, thyroid carcinoma (THCA), UCEC, HNSC, and TGCT showed relatively lower methylation levels of CD244." (PMID 38633624, 2024).
Autoimmunity (4 papers, 2018 to 2025). The occurrence of an immune reaction against the organism's own cells or tissues. "Moreover, mutation of the CD244 gene is closely linked to the risk of autoimmunity." (PMID 30279688, 2018). "Investigating the role of monocyte CD244 may prove to be important in mechanisms of tolerance and autoimmunity." (PMID 28593610, 2018).
colorectal cancer (4 papers, 2024 to 2026). A primary or metastatic malignant neoplasm that affects the colon or rectum. "Some T cell exhaustion markers like CD244 are potential prognostic biomarkers and therapeutic targets in colorectal cancer." (PMID 38633624, 2024).
COVID-19 (4 papers, 2020 to 2022). A disease caused by infection with severe acute respiratory syndrome coronavirus 2. "Our study found that the expression levels of PD-1 and CD244 on NK cells are significantly elevated in patients with COVID-19 compared to healthy volunteers, which signifies an exhausted state of NK cells in patients with COVID-19." (PMID 33154753, 2020). "In COVID-19 patients, the CD244 and PD-1 expression levels of CD8+ and CD4+ T cells were significantly higher and CD27 expression levels of CD8+ T cells were significantly lower than healthy controls." (PMID 33154753, 2020). "More importantly, the significantly elevated expression levels of PD-1 and CD244 on CD8+ T cells indicate that SARS-CoV-2 induces T cell exhaustion in COVID-19 patients." (PMID 33154753, 2020). "More importantly, elevated expression of regulatory molecules, such as CD244 and programmed death-1 (PD-1), on NK cells and T cells, as well as decreased serum cytotoxic effector molecules including perforin and granzyme A, were detected in patients with COVID-19." (PMID 33154753, 2020). "COVID-19 patients displayed an immune phenotype characterized by increased HLA-DR+CD38+ and PD-1+ CD4+ and CD8+ T cells, and elevated CD8+CD244+ lymphocytes, compared to healthy controls." (PMID 33717195, 2021).
lung carcinoma (4 papers, 2021 to 2024). "With recent in-depth research, studies revealed that CD244 is a promising biomarker and immunotherapy target in some cancers, such as lung cancer." (PMID 38633624, 2024). "In research on tumor diseases, it has also been found that CD244 is highly expressed on the surface of T cells in a mouse model of lung cancer, inhibiting the cytokine secretion capacity of T cells while promoting T cell apoptosis, leading to T cell exhaustion." (PMID 39578914, 2024). "This indicated that CD244 functioned as an inhibitory receptor in lung cancer." (PMID 33841431, 2021). "CD244 expression on CD8+ T cells impaired the production of cytokines and increased apoptosis in mice with lung cancers." (PMID 38633624, 2024). "The expression of CD244 in CD4+ and CD8+ T cells was increased in a mouse model of lung cancer, and these cells exhibited more apoptosis and decreased secretion of anti-tumor cytokines." (PMID 33841431, 2021).
depression (3 papers, 2023 to 2025). "We observed an increase in CD3 + CD160 + CD244 + T cells in SLE patients with persistent proteinuria, high disease activity, and C3/C4 depression." (PMID 38650001, 2024).
head and neck squamous cell carcinoma (3 papers, 2022 to 2024). A squamous cell carcinoma that arises from any of the following anatomic sites: lip and oral cavity, nasal cavity, paranasal sinuses, pharynx, larynx, and salivary glands. "Our findings also provide insights into the association between CD244 expression and signatures of immunosuppressive monocytes, as previously reported in mouse models of head and neck squamous cell carcinoma." (PMID 38424542, 2024). "When compared the growth of B16F10 tumors in WT and CD244 whole knockout (CD244−/−) mice, we found that the growth of B16F10 tumors was significantly slower in CD244−/− mice than in WT mice, consistent with previous results in a head and neck squamous cell carcinoma model." (PMID 38424542, 2024). "The results demonstrated a negative correlation between the clinical-pathological stages and CD244 expression levels in UCEC, testicular germ cell tumors (TGCT), READ, COAD, and head and neck squamous cell carcinoma (HNSC)." (PMID 38633624, 2024). "CD244 expression was increased in head and neck squamous cell carcinoma (HNSCC) and negatively correlated with CD8+ T-cell infiltrate, suggesting that CD244 could be an immunotherapy target in HNSCC." (PMID 35237510, 2022). "We subsequently explored the relationship between survival rate and CD244 expression, and found the positive relationship in patients with adrenocortical carcinoma (ACC), head and neck squamous cell carcinoma (HNSC), skin cutaneous melanoma (SKCM), and uterine corpus endometrial carcinoma (UCEC)." (PMID 38633624, 2024).
hepatitis C (3 papers, 2014 to 2025). "However, increased plasma levels of CD244 have been reported in hepatitis C infection." (PMID 39206195, 2024).
HIV-1 infection (3 papers, 2009 to 2019). The type species of lentivirus and the etiologic agent of acquired immunodeficiency syndrome (AIDS). "High CD244 expression on CD8+ T cells has been shown in patients with HIV-1 infection, acute infectious mononucleosis and myelodysplastic syndrome." (PMID 19997502, 2009). "The expression of CD244 on CD8+ T cells correlated with T cell activation, as has been reported in patients with HIV-1 infection, acute infectious mononucleosis, and myelodysplastic syndrome." (PMID 19997502, 2009).
liver disease (3 papers, 2011 to 2024). "The identification of specific drugs targeting HLA-DRB5, GJB3, HSD17B13, and CD244 for various indications, such as cancer, metabolic diseases, and liver disorders, further strengthens their potential as therapeutic targets in LUAD." (PMID 39092217, 2024).
X-linked lymphoproliferative syndrome (3 papers, 2012 to 2019). X-linked lymphoproliferative disease is a hereditary immunodeficiency characterized, in the majority of cases, by an inadequate immune response to infection with the Epstein-Barr virus (EBV). "On the other hand, CD244 can inhibit NK cell activation in the absence of functional SAP, such as occurs in cells from patients with X-linked lymphoproliferative syndrome." (PMID 24626474, 2014).
acute graft versus host disease (2 papers, 2023 to 2024). A syndrome of immunologically mediated tissue damage that may occur following an allogeneic transplant, usually affecting the skin, liver, and GI tract. "Differential expression analysis showed that low levels of IL18-R1, LIF-R and IL22-RA1 were seen in patients who subsequently developed acute graft versus host disease (AGvHD) whilst lower levels of CD244, TSLP, IL15-RA and IL-33 were observed in patients who developed chronic GvHD." (PMID 38235129, 2023). "We found weak genetic associations between polymorphisms in the CD226, CD244, FCGR3A, KLRD1, NCR3, and PVRIG genes, and the risks for relapse, acute GVHD, and chronic GVHD in the HSCT discovery cohort but not in the replication cohort." (PMID 39506082, 2024).
acute lymphoblastic leukemia (2 papers, 2024 to 2025). Leukemia with an acute onset, characterized by the presence of lymphoblasts in the bone marrow and the peripheral blood. "Furthermore, research suggests that the lower SAP/CD244 expression ratio in peripheral blood CD8+ T cells of patients with acute lymphocytic leukemia indicates an inhibitory role of CD244." (PMID 39578914, 2024).
cutaneous melanoma (2 papers, 2022 to 2024). A primary melanoma arising from atypical melanocytes in the skin. "The key immune checkpoints including BTLA, CD86, CD244, and PDCD1 are recognized as predictors of sentinel lymph node metastasis in cutaneous melanoma." (PMID 35069935, 2022). "Then, through the 'forest plot' R package, we found that CD244 could be as a protective factor in multiple tumor types, such as adrenocortical carcinoma (ACC), HNSC, skin cutaneous melanoma (SKCM) and UCEC." (PMID 38633624, 2024).
dermatomyositis (2 papers, 2016 to 2023). Dermatomyositis (DM) is a type of idiopathic inflammatory myopathy characterized by evocative skin lesions and symmetrical proximal muscle weakness. "Enriched genes including S100A12, MPO (myeloperoxidase), S100A8, CXCL10, S100A9, CD244, CD244,and TLR7 have been linked to dermatomyositis." (PMID 38137330, 2023).
diabetes (2 papers, 2024 to 2025). "For another eight biomarkers (TNFβ, GDNF, IL-18R1, LIF-R, CD244, CD6, FGF-5, IFNγ), a significant interaction by diabetes type was observed." (PMID 39799156, 2025).
inflammatory bowel disease (2 papers, 2021 to 2024). A spectrum of small and large bowel inflammatory diseases of unknown etiology. "In inflammatory bowel disease (IBD), the interaction between CD244 and its ligands may promote the inflammatory response." (PMID 39423200, 2024).
latent infection (2 papers, 2011 to 2013). "Mean fluorescent intensity (MFI) of CD244/2B4 expression on antigen-responsive CD4+ T cells was also significantly higher in retreatment active TB patients as compared with latent infection individuals (p = 0.0006) and new active TB patients (p = 0.0029)." (PMID 23638187, 2013). "New TB patients had significantly elevated expression of CD244/2B4 as compared with latent infection individuals (p = 0.0029)." (PMID 23638187, 2013). "We found that pulmonary TB patients had significantly elevated CD244/2B4 expression on M. tuberculosis antigen-specific CD4+ T cells compared with latent infection individuals." (PMID 23638187, 2013). "The expression of CD244 on antigen-responsive CD4+ T cells was elevated in retreatment TB patients compared with latent infection individuals (p = 0.0048) and new TB patients (p = 0.0038)." (PMID 23638187, 2013). "In this study, we investigated the expression and function of CD244/2B4 on CD4+ T cells from active TB patients and latent infection individuals." (PMID 23638187, 2013). "In this study, we investigated the expression and function of CD244/2B4 on CD4+ T cells from active TB patients, latent infection individuals and healthy controls." (PMID 23638187, 2013).
myositis (2 papers, 2007 to 2016). "Poor outcome in patients with myositis following immunosuppressive therapy was linked to persistence of CD244+ (CD28null) T cells in muscle tissue, suggesting their resistance against immunosuppression." (PMID 27039301, 2016). "We have previously demonstrated that the majority of CD244 expressing T cells display a CD28null phenotype in the circulation of myositis patients." (PMID 27039301, 2016). "Also, using a triple immunofluorescence technique, CD244+ cells in myositis muscle tissue stained mostly positive for CD3; therefore these cells were considered CD28null T cells and not NK cells." (PMID 27039301, 2016). "We have demonstrated that a majority of CD28null T cells (89 % of the CD4+CD28null and 98 % of the CD8+CD28null T cells) in the circulation of patients with myositis stained positive for CD244 and strong correlations were observed between CD244+ cells expressing CD3+ and CD28null T-cell subsets." (PMID 27039301, 2016). "We have demonstrated that the current treatment regime based on high doses of glucocorticoids in combination with conventional immunosuppressive agents is insufficient to eliminate CD3+ and CD244+ cells (focusing on the subgroup of myositis patients displaying such cells)." (PMID 27039301, 2016). "In this study, we could demonstrate that CD244+ cells (a validated surrogate marker for CD28null T cells in myositis muscle tissue) dominate the T-cell infiltrates over FOXP3+ cells (a marker for regulatory T cells) in inflamed myositis muscle tissue." (PMID 27039301, 2016). "However, this is the first study which investigates the frequencies FOXP3+ in relation to the CD244+ cells and how their relative proportion is affected in myositis muscle tissue by immunosuppressive treatment." (PMID 27039301, 2016). "Muscle biopsy sections were utilized to study CD3+, CD244+ and FOXP3+ cells in myositis muscle tissue." (PMID 27039301, 2016). "When comparing the proportions (% of total T cells), CD244+ cells (median 33.4 %, range 0–85.7 %) were present in approximately 10-fold higher proportion compared to FOXP3+ cells (median 3.4 %, range 0–71.1 %, p = 0.01) in the myositis muscle tissue." (PMID 27039301, 2016).
ovarian carcinoma (2 papers, 2021 to 2024). A malignant neoplasm originating from the surface ovarian epithelium. "All these data showed that ITK could act as a cancer suppressor gene in patients with ovarian cancer and had a similar function to CD244 and SOCS1." (PMID 34702300, 2021). "Therefore, like CD244, CD24 is also likely to exhibit dual opposing functions depending on the molecular basis of ovarian cancer cells." (PMID 38360723, 2024).
polymyositis (2 papers, 2016 to 2023). A rare idiopathic inflammatory myopathy characterized by symmetric proximal muscle weakness and elevated muscle enzymes. "Enriched genes including CXCL11 and CD244 are considered potential biomarkers for polymyositis." (PMID 38137330, 2023).
pulmonary TB (2 papers, 2013 to 2020). "PBMCs from patients with pulmonary TB and healthy controls were stained with fluorescence-labeled CD3, CD4 and CD244/2B4 antibodies and analyzed by flow cytometry." (PMID 23638187, 2013).
thyroid cancer (2 papers, 2024 to 2025). "The forward MR analysis results suggested potential associations between circulating CD244 levels and increased risks in thyroid cancer." (PMID 40072746, 2025). "There is a suggestive association between natural killer cell receptor 2B4 (CD244) (IVW-OR: 1.19, 95% CI 1.05–1.36, p = 0.007) and an increased risk of thyroid cancer." (PMID 40072746, 2025). "Therefore, in future thyroid cancer treatments, strategies targeting CD244 inhibition may serve as an additional approach to existing immune checkpoint inhibitors or as a complement to conventional chemotherapy approaches." (PMID 40072746, 2025).
tropical spastic paraparesis (2 papers, 2013 to 2014). "Blockade of CD244/2B4 receptor signaling inhibits degranulation and IFN-γ production in CD8+ T cells of patients with HTLV-I-associated myelopathy/tropical spastic paraparesis (HAM/TSP), suggesting that CD244/2B4 might play roles in promoting inflammatory neurological disease." (PMID 23638187, 2013).